VDR (vitamin D receptor)
Diseases named in the same sentence as VDR in open-access papers (continued):
Sharing a sentence is not in itself a finding about the gene and the disease.
endometrial polyp (1 paper, 2025). A benign nodular lesion protruding above the surface of the endometrium. "The cross-sectional design precludes causal inference between VDR expression and the development of endometrial polyps." (PMID 41394244, 2025). "VDR expression patterns might inform risk stratification strategies for endometrial polyp management, particularly in identifying lesions requiring closer surveillance or more aggressive intervention." (PMID 41394244, 2025). "Individual case-level immunohistochemical scores for VDR expression in endometrial polyps and adjacent normal endometrium." (PMID 41394244, 2025). "Distribution of composite Van Slooten scores for vitamin D receptor (VDR) expression in endometrial polyps and normal endometrium." (PMID 41394244, 2025). "The differential VDR expression observed in endometrial polyps provides important insights for translational medicine applications." (PMID 41394244, 2025). "The pattern of increased VDR expression observed in endometrial polyps is consistent with findings in other benign hyperplastic conditions." (PMID 41394244, 2025). "This study demonstrates that VDR expression is significantly increased in endometrial polyps compared to adjacent normal endometrium, with 58.8% of polyps showing positive immunostaining versus 23.5% of normal tissue." (PMID 41394244, 2025). "Instead, we sought to generate preliminary data on VDR expression in endometrial polyps to guide future, adequately powered studies." (PMID 41394244, 2025). "A comparative non-parametric analysis was performed to evaluate differences in VDR expression between endometrial polyps and paired normal endometrium." (PMID 41394244, 2025). "This study provides novel evidence of differential VDR expression in endometrial polyps, demonstrating significantly increased receptor levels compared to adjacent normal endometrium." (PMID 41394244, 2025). "The demonstration of increased VDR expression in endometrial polyps provides a rational biological basis for exploring vitamin D analogs and VDR-related pathways as potential therapeutic targets." (PMID 41394244, 2025). "Distribution of staining intensity and fraction of positively stained cells for vitamin D receptor (VDR) expression in endometrial polyps and normal endometrium." (PMID 41394244, 2025). "The mechanistic rationale for VDR upregulation in endometrial polyps likely involves the complex interplay between estrogen dominance and vitamin D signaling." (PMID 41394244, 2025). "In this study, we hypothesized that endometrial polyps would demonstrate increased VDR expression compared with adjacent normal endometrium, consistent with compensatory upregulation in response to hyperplastic stimuli." (PMID 41394244, 2025). "Given vitamin D's established roles in modulating estrogen receptor expression, suppressing inflammatory cytokines, and promoting apoptosis - processes central to endometrial polyp pathogenesis - investigating VDR expression in these lesions represents a logical translational approach." (PMID 41394244, 2025). "Overall, the results demonstrate a consistent and statistically significant increase in VDR immunoexpression in endometrial polyps compared with adjacent normal endometrium, supporting the hypothesis of receptor modulation associated with proliferative activity in benign endometrial lesions." (PMID 41394244, 2025). "However, no studies have directly examined VDR presence or functional significance in endometrial polyps, representing a significant knowledge gap given the documented protective role of vitamin D signaling in analogous hyperplastic conditions." (PMID 41394244, 2025).
endometrial tumour (1 paper, 2025). "For example, one study showed that vitamin D nuclear receptor (VDR) expression is significantly higher in endometrial tumour samples with a lower histological grade." (PMID 40754672, 2025).
enteritis (1 paper, 2023). Inflammation of the small intestine. "Compared with mice at 10 months old, VDR is highly expressed in young mice 28-30, so Parkin's regulation of VDR expression may take a leading role in the occurrence of enteritis prior to its role in mitophagy." (PMID 37056928, 2023).
enteropathy (1 paper, 2022). "Targeting VDR may inhibit intestinal inflammation and establish host defense against intestinal bacteria, and treatment of NSAID-associated enteropathy with VDR activators can be explored in the future." (PMID 35222032, 2022).
enthesopathy (1 paper, 2023). "By P14, Hyp entheses have a decrease in immunoreactivity for the VDR compared with WT entheses, suggesting that a decrease in VDR expression in Hyp entheses contributes to the impaired 1,25D action and, thus, enthesopathy development." (PMID 37490334, 2023). "Deletion of the vitamin D receptor in scleraxis-expressing cells resulted in enthesopathy, indicating that 1,25D acted directly on enthesis cells to regulate enthesopathy development." (PMID 37490334, 2023). "Loss of the VDR in Scx+ cells starting on P30 does not result in enthesopathy." (PMID 37490334, 2023). "Based on our findings that 1,25D acts on enthesis cells to suppress BMP and IHH signaling, the decrease in VDR expression in Hyp entheses likely also contributes to the impaired 1,25D action in Hyp entheses, leading to increased BMP and IHH signaling and enthesopathy development." (PMID 37490334, 2023).
eosinophilic esophagitis (1 paper, 2026). Eosinophilic esophagitis (EoE) is a chronic, allergic disease of the esophagus characterized clinically by symptoms of esophageal dysfunction (including vomiting, dysphagia, feeding disorders, food impaction and abdominal pain) which persist after treatment with proton pump inhibitors (PPIs). "For example, VDR expression within esophageal submucosal glands may influence fibrosis in eosinophilic esophagitis, while in the stomach VDR is associated with malignancy and Heliocobacter pylori infection." (PMID 42232580, 2026).
ependymoma (1 paper, 2022). A WHO grade II, slow growing tumor of children and young adults, usually located intraventricularly. "In the case of ependymoma and medulloblastoma, no significant VDR expression was detected in our studies." (PMID 35884356, 2022). "Based on the observations made during the evaluation, non-significant VDR expression was characteristic for ependymoma and medulloblastoma." (PMID 35884356, 2022).
Erythema (1 paper, 2015). Redness of the skin, caused by hyperemia of the capillaries in the lower layers of the skin. "None of the studied VDR SNPs genotypes segregated with facultative melanin, facultative erythema, constitutive erythema, or differences in melanin or erythema." (PMID 26540116, 2015).
esophagitis (1 paper, 2006). An acute or chronic inflammatory disease affecting the esophageal wall. "The relative quantity of VDR mRNA was not significantly different in normal esophagus (1 ± 0.67) compared to esophagitis (0.78 ± 0.89, p = ns), BE (2.23 ± 1.62, p = ns) and AC (0.97 ± 0.99, p = ns), suggesting a constitutive expression of this receptor in these different esophageal conditions." (PMID 17054793, 2006).
fibrosarcoma (1 paper, 2017). A malignant mesenchymal fibroblastic neoplasm affecting the soft tissue and bone. "In particular, in homozygous recessive patients for Fok1 SNPs of VDR a high rate of histological regression and BRAF (B- Rapidly Accelerated Fibrosarcoma gene) mutation were observed." (PMID 29100280, 2017).
foetal macrosomia (1 paper, 2022). "While a few studies have demonstrated a link between GDM and foetal macrosomia, a recent meta-analysis found that specific patterns of VDR polymorphisms influence birth weight and other anthropometric neonatal outcomes." (PMID 36071390, 2022).
Follicular Cyst (1 paper, 2021). Cyst due to the occlusion of the duct of a follicle or small gland. "In the letrozole-treated group, VDR was detected in cells within the luteinized wall of follicular cysts." (PMID 33095902, 2021). "In addition, VDR was detected in the luteinized wall of the follicular cysts." (PMID 33095902, 2021).
fungal keratitis (1 paper, 2022). "When corneal epithelial cells were infected by Fusarium solani, researchers observed an upregulation of the VDR via the TLR2/1-VDR pathway, identifying the role of the VDR pathway as a potential target for upregulating CAMP to treat fungal keratitis." (PMID 35722307, 2022).
Gardner syndrome (1 paper, 2016). Gardner syndrome is a severe form of familial adenomatous polyposis characterized by multiple adenomas in the colon and rectum associated with prominent extracolonic features including osteomas and multiple skin and soft tissue tumors. "The effects of VDR ablation on ACF in the proximal large intestine (cecum) of Apc1638N/+ mice is reminiscent, not only of the Gardner syndrome's variant of FAP, but also of inactivation of retinoblastoma protein (Rb) in Apc1638N/+ mice." (PMID 27768599, 2016).
germ cell tumor (1 paper, 2018). A benign or malignant, gonadal or extragonadal neoplasm that originates from germ cells. "The tissue of 52 patients with germ cell tumors was analyzed for VDR expression by immunohistochemistry." (PMID 29765521, 2018).
gingivitis (1 paper, 2025). A disorder involving inflammation of the gums; may affect surrounding and supporting structures of the teeth. "In particular, according to the reported studies, genetic polymorphisms of VDR TaqI (rs731236), CD14 −260C/T, IL10-592-C, IL-1Ra, and TLR4-299-G were associated with higher risk of developing gingivitis." (PMID 41300760, 2025). "Thus, it is necessary to identify specific polymorphisms related to the disease, in this case TaqI (rs731236) gene polymorphism is correlated with the onset of gingivitis, but genetic polymorphisms FokI (rs2228570) and BglI (rs739837) in VDR are not." (PMID 41300760, 2025).
glomerular diseases (1 paper, 2023). "A RAAS blocker, losartan, could reduce miR-193a in glomerular diseases directly or indirectly via VDR upregulation." (PMID 38136614, 2023).
glottic carcinoma (1 paper, 2025). "Associations between VDR/CYP24A1 polymorphisms and the recurrence risk of glottic carcinoma further emphasize the need for genotype-guided therapy." (PMID 41246358, 2025).
graft versus host disease (1 paper, 2018). An immune system disorder that occurs after allogeneic hematopoietic stem cell transplant and is a reaction of donor immune cells against host tissues. "Thus, the vitamin D receptor and its mediation on immune signalling appear to have an impact on immune reconstitution after HSCT and the risk of infection and graft versus host disease." (PMID 30205552, 2018).
H. pylori (1 paper, 2020). "H. pylori-infection, however, slightly enhanced CAMP expression at both the mRNA and protein levels in both WT and VDR-KD mice." (PMID 33194806, 2020).
hair disorders (1 paper, 2026). "This comprehensive analysis underscores the significance of VDR‐targeted approaches in the future management of hair disorders and highlights the importance of continued research in this field." (PMID 41473843, 2026). "As research continues to unravel the complexities of VDR signaling, the integration of molecular insights with clinical applications will be essential for developing more effective, personalized treatments for patients with hair disorders." (PMID 41473843, 2026). "Combined with advanced drug delivery systems, including nanocarriers and tissue‐specific targeting strategies, these therapeutic approaches may provide novel treatment options for patients with VDR‐related hair disorders." (PMID 41473843, 2026). "The vitamin D receptor (VDR) signaling system has emerged as a crucial regulator of hair follicle biology and potential therapeutic target for hair disorders." (PMID 41473843, 2026).
hand osteoarthritis (1 paper, 2006). "We examined whether polymorphisms of the vitamin D receptor (VDR) gene was associated with individual risk of hand osteoarthritis (OA)." (PMID 16507122, 2006).
hearing loss (1 paper, 2024). "It has been described that downregulation of VDR signaling is associated with benign paroxysmal positional vertigo, sensorineural hearing loss, and other inner ear disorders in humans." (PMID 39201406, 2024).
helminth infection (1 paper, 2019). "Murine studies revealed that inflammatory maternal signals elicited by chronic helminth infection within the placenta imprint a distinct gene expression profile related to the Vitamin-D-receptor (VDR)-inflammation-axis." (PMID 31673046, 2019).
hepatoblastoma (1 paper, 2022). Hepatoblastoma (HB) is a malignant hepatic tumor and is the most common pediatric liver cancer. "Based on these findings, it is presumed that immunohistochemical examination of the tumor VDR pattern in hepatoblastoma is recommended, and in cases of significant VDR expression, the administration of vitamin D or its analogs may be reasonable as a part of oncotherapy." (PMID 35884356, 2022). "Due to statistical correctness, the statistical analysis does not include the results of hepatoblastoma VDR expression measurement." (PMID 35884356, 2022).
Hypergonadotropic hypogonadism (1 paper, 2025). Reduced function of the gonads (testes in males or ovaries in females) associated with excess pituitary gonadotropin secretion and resulting in delayed sexual development and growth delay. "Furthermore, VDR-deficient mice were found to develop hypergonadotropic hypogonadism." (PMID 40365228, 2025).
Hyperkeratosis (1 paper, 2025). Hyperkeratosis is a histopathological term defining a thickened stratum corneum and may be present in many different skin conditions, with many possible overlaps. "Given the hyperkeratosis observed in VDR-KO rats through HE staining, we conducted Western blotting using the antibody against the keratin marker Krt14 and anti-pan-keratin antibody (PCK26), which detects rat keratin 1 (66 kDa), keratin 5 (58 kDa), and keratin 8 (52 kDa)." (PMID 39796272, 2025).
Hypocholesterolemia (1 paper, 2021). An decreased concentration of cholesterol in the blood. "In the present study, we found hypocholesterolemia, high prevalence of VDR FokI C allele, and low vitamin D levels among children and adults with SCD from Kurdistan of Iraq." (PMID 34261187, 2021).
idiopathic hypercalciuria (1 paper, 2015). A rare renal disease characterized by persistent excess urinary calcium excretion in the absence of an underlying systemic disease and hypercalcemia. "In addition, levels of the vitamin D receptor (VDR) and its genetic polymorphisms were also indicated to be associated with idiopathic hypercalciuria (IH)." (PMID 26089600, 2015).
Immunodeficiency (1 paper, 2021). Failure of the immune system to protect the body adequately from infection, due to the absence or insufficiency of some component process or substance. "In this study, low levels of vitamin D receptor in SID-HIV patients could occur through a chronic inflammatory process associated with severe immunodeficiency." (PMID 33664952, 2021). "There were significantly lower serum vitamin D receptor levels and significantly higher HMGB1 protein serum levels in the HIV group with severe immune deficiency (SID-HIV) than the HIV group with mild immune deficiency (MID-HIV) and the healthy control (HC) group." (PMID 33664952, 2021). "This study aimed to examine differences and correlation of vitamin D receptor and HMGB1 protein levels in HIV patients with mild and severe immunodeficiency and healthy control participants." (PMID 33664952, 2021). "Strong negative correlation between VDR and HMGB1 in different immunodeficiency statuses suggesting an important role of vitamin D in inflammation control in HIV infection." (PMID 33664952, 2021).
Impaired glucose tolerance (1 paper, 2018). An abnormal resistance to glucose, i.e., a reduction in the ability to maintain glucose levels in the blood stream within normal limits following oral or intravenous administration of glucose. "Other genetic factors, such as genetic polymorphisms of vitamin D-binding protein (DBP) or vitamin D receptor (VDR), may affect vitamin D status and may play a role in impaired glucose tolerance or T2DM." (PMID 29743959, 2018).
infertility disorder (1 paper, 2018). Inability to conceive for at least one year after trying and having unprotected sex. "There is some disagreement in the literature regarding the relationship between VDR polymorphisms and infertility disorders." (PMID 29892263, 2018). "Altogether, these data highlight the relevance of the TaqI polymorphism under different conditions and suggest the need for further studies investigating the relationship between VDR polymorphisms and 25(OH)D serum concentrations in different pathologies, including infertility disorders." (PMID 29892263, 2018).
insomnia (1 paper, 2024). A sleep disorder characterized by difficulty in falling asleep and/or remaining asleep. "This suggests that adequate vitamin D levels may help mitigate the severity of insomnia, likely due to the influence of the vitamin D receptor (VDR) on genes related to hormones, neurotransmitters, and circadian rhythm regulation." (PMID 39619283, 2024).
interstitial lung disease (1 paper, 2024). A diverse group of lung diseases that affect the lung parenchyma. "IPF and other types of interstitial lung disease (ILD) patients display decreased serum VitD concentrations and lung Vitamin D receptor (VDR)." (PMID 38570797, 2024).
intestinal inflammation (1 paper, 2022). "For several organ dysfunctions, the vitamin D/VDR signaling pathway is essential in regulating connectivity components and maintaining epithelial barrier integrity, including intestinal inflammation, infection, and chronic inflammatory lung diseases." (PMID 36211484, 2022).
intracerebral hemorrhage (1 paper, 2025). A cerebrovascular disorder characterized by bleeding into one or both cerebral hemispheres including the basal ganglia and the cerebral cortex. "The Vitamin D Receptor (VDR) is an emerging therapeutic target for neurological injuries, yet its role in neuronal ferroptosis and mitochondrial dynamics following intracerebral hemorrhage (ICH) remains undefined." (PMID 41125493, 2025).
invasive carcinoma (1 paper, 2010). A carcinoma that is not confined to the epithelium, and has spread to the surrounding stroma. "An interesting finding is the correlation between the expression of the VDR and the ER in both in situ and invasive carcinomas." (PMID 20831823, 2010).
keratoconus (1 paper, 2023). A degenerative, structural disorder of the eye, characterized by a cone-shaped protrusion of the cornea. "vitamin D receptor polymorphism is associated with keratoconus development." (PMID 35915233, 2023).
laryngeal carcinoma (1 paper, 2025). Carcinoma that arises from the laryngeal epithelium. "Although direct studies in laryngeal cancer are lacking, existing evidence suggests that: VDR is expressed in laryngeal cancer cells and influences tumorigenesis and prognosis." (PMID 41246358, 2025).
leishmaniasis (1 paper, 2023). Infectious disease that is transmitted through the bite of hematophagous female phlebotomine sand flies. "few studies have examined the relationship between vitamin D and the VDR gene polymorphism and protozoal infection including leishmaniasis." (PMID 37319132, 2023).
leukopenia (1 paper, 2016). "This study provides a unique insight into the association among the very low level of vitamin D3, the decrease of VDR, leukopenia, and 5-HTTLPR extended to emotional dysfunction." (PMID 26903713, 2016). "The aim of the work was to highlight the association among severe hypovitaminosis D3, reduction of vitamin D receptor (VDR), leukopenia, and 5-HTTLPR in patients with long-term AN and BN." (PMID 26903713, 2016).
Listeria infection (1 paper, 2015). "On the contrary, VDR KO mice compared to controls showed only a slight delay in clearance of Listeria infection in young and old mice, even though old VDR KO mice had lower memory CD4+ and CD8+ T cell numbers." (PMID 26035244, 2015).